TNS3 (tensin 3)
Description:
May act as a protein phosphatase and/or a lipid phosphatase (Probable). Involved in the dissociation of the integrin-tensin-actin complex. EGF activates TNS4 and down-regulates TNS3 which results in capping the tail of ITGB1. Increases DOCK5 guanine nucleotide exchange activity towards Rac and plays a role in osteoclast podosome organization (By similarity). Enhances RHOA activation in the presence of DLC1. Required for growth factor-induced epithelial cell migration; growth factor stimulation induces TNS3 phosphorylation which changes its binding preference from DLC1 to the p85 regulatory subunit of the PI3K kinase complex, displacing PI3K inhibitor PTEN and resulting in translocation of the TNS3-p85 complex to the leading edge of migrating cells to promote RAC1 activation. Meanwhile, PTEN switches binding preference from p85 to DLC1 and the PTEN-DLC1 complex translocates to the posterior of migrating cells to activate RHOA. Acts as an adapter protein by bridging the association of scaffolding protein PEAK1 with integrins ITGB1, ITGB3 and ITGB5 which contributes to the promotion of cell migration. Controls tonsil-derived mesenchymal stem cell proliferation and differentiation by regulating the activity of integrin ITGB1.
Synonyms: TEM6; TENS1; H_NH0549I23.2; FLJ13732
Tractability: PROTAC: ubiquitination databases record sites on it; its protein half-life has been measured.
Target class: Enzyme; Phosphatase
Gene: Protein-coding gene on chromosome 7 (47,275,154 to 47,582,558, reverse strand). Ensembl gene ENSG00000136205.
Subcellular location: Cell junction, focal adhesion; Cell projection, podosome
Subcellular location (Human Protein Atlas): Focal adhesion sites
Pathways (Reactome):
Signal Transduction: MET interacts with TNS proteins
Gene Ontology:
Molecular function: protein binding
Biological process: positive regulation of Rac protein signal transduction
Cellular component: focal adhesion; cytosol; podosome
Genetic constraint (gnomAD): Loss-of-function variants: 42 observed, 127.1 expected, observed/expected ratio (o/e) 0.33, 90% interval 0.26 to 0.43. The upper end of that interval is the gene's LOEUF score, 0.43, which puts it in group 1 of 6, group 1 being the genes least tolerant of losing a copy. Missense variants: 1,655 observed, 1,803.7 expected, observed/expected ratio (o/e) 0.92, 90% interval 0.88 to 0.96. Synonymous variants: 783 observed, 745.34 expected, observed/expected ratio (o/e) 1.05, 90% interval 0.99 to 1.11.
Homologues: Orthologues: chimpanzee TNS3 (99% identical), macaque TNS3 (97% identical), rat Tns3 (83% identical), mouse Tns3 (83% identical), pig TNS3 (83% identical), dog TNS3 (79% identical), guinea pig TNS3 (79% identical), tropical clawed frog TNS3 (52% identical). Paralogues in human: TNS1 (46% identical), PTEN (8% identical), TMEM266 (7% identical), TPTE2 (6% identical), TPTE (6% identical), HVCN1 (4% identical).
Diseases named in the same sentence as TNS3 in open-access papers:
TNS3 is named in the same sentence as 38 diseases in open-access papers, as found by Europe PMC text mining. Sharing a sentence is not in itself a finding about the gene and the disease. The quoted sentences say what the papers report.
breast carcinoma (12 papers, 2016 to 2025). "The gene expression and DNA methylation on CpG island of TNS3 have been associated with breast cancer and renal cell carcinoma." (PMID 33824309, 2021). "Furthermore, constitutive miR-375 expression in breast cancer cells directly suppresses TNS3, enhancing tumor-associated macrophage migration and accelerating tumorigenesis." (PMID 40906372, 2025). "Furthermore, constitutive miR-375 expression in breast cancer cells directly targets TNS3, enhancing tumor-associated macrophage migration and facilitating tumorigenesis, highlighting TNS3’s role in modulating the tumor microenvironment beyond direct effects on cancer cells." (PMID 40906372, 2025). "Consistently, TNS3 knockdown inhibited cell migration in MDA-MB-468 breast cancer cells, though interestingly in an EGF induction-dependent manner." (PMID 40906372, 2025). "Conversely, exogenous introduction of SUV420H2 into MDA-MB-231 breast cancer cells downregulated TNS3 and reduced invasion, suggesting that TNS3 can facilitate migration/invasion." (PMID 40906372, 2025). "A study using a breast cancer cell line suggests that TNS3 silencing activates the Rho-GAP function of DLC1 through releasing an autoinhibitory effect, and thereby elevating the level of RhoA-GTP." (PMID 37668682, 2023). "These analyses recapitulated known transcript-level regulation of cancer-related genes and also revealed an unannotated isoform of TNS3 as a novel driver of breast cancer." (PMID 34811492, 2021). "Paxillin and tensin 3 mRNA and protein levels were reduced in macrophages upon coculture with breast cancer cells, as well as after treatment with miR-375 containing supernatants from apoptotic MCF-7 cells." (PMID 31766495, 2019). "The roles of TNS3 in breast cancer are notably context-dependent." (PMID 40906372, 2025). "TNS3 exhibits context-dependent roles in thyroid, gastric, and breast cancers." (PMID 40906372, 2025). "In recent years, studies involving tensins, especially tensin-3 (TNS3), mainly focused on tumorigenesis and metastasis, showing that its dysregulation is closely associated with multiple cancers including lung cancer, breast cancer and kidney cancer." (PMID 37668682, 2023). "In addition, downregulation of TNS1, TNS2 or TNS3 reduces the invasiveness of ovarian and breast cancer cell lines by impairing integrin internalization and focal adhesion turnover." (PMID 37510408, 2023). "This might be because the effect of TNS3 was canceled out by the dependence of the TNS3 isoform switch on the breast cancer subtype." (PMID 34811492, 2021). "In breast cancer, it is upregulated by EGF, displacing TNS3 from actin to promote migration." (PMID 40906372, 2025). "TNS3, identified in 2004, has been reported to serve as an oncogene, which is based on Src family kinases (mainly Src) mediated tyrosine phosphorylation of its SH2 domain in several advanced cancers, such as non-small cell lung cancer, breast cancer, and melanoma." (PMID 34047714, 2021). "Similarly, tensin 3 acts as a link between the extracellular matrix and the cytoskeleton and functionally contributes to the switch between adhesive and non-adhesive states in cancer cells, including breast cancer." (PMID 31766495, 2019).
lung carcinoma (4 papers, 2019 to 2025). "We genotyped the seven 3′UTR SNPs in NR5A2, LPP, and TNS3 to determine the potential association with the susceptibility to lung cancer." (PMID 30621612, 2019). "In this study, we found that three polymorphisms (rs1064607, rs3796283, and rs2378456) in the 3′-UTR of LPP and TNS3 rs9876 polymorphism were significantly associated with susceptibility to lung cancer." (PMID 30621612, 2019). "Moreover, TNS3 rs9876 polymorphism was associated with the lymphatic metastasis of lung cancer patients." (PMID 30621612, 2019). "In A549 cells, miR-200a-3p promoted cell migration by directly suppressing TNS3 expression, indicating TNS3’s anti-tumorigenic function in lung cancer." (PMID 40906372, 2025). "Endogenous TNS3 contributes to cell migration, anchorage-independent growth, and tumorigenesis in cell lines derived from advanced lung cancer." (PMID 30621612, 2019). "Here, we found that TNS3 acts as an oncogene, affecting regulation of methylation in lung cancer." (PMID 34002017, 2021). "We, therefore, propose that These SNPs may affect LPP or TNS3 expression in lung cancer by differential mRNA stability and binding activity of miR-144 and miR-182." (PMID 30621612, 2019). "Thus, LPP and TNS3 may have an important role of in the tumorigenesis and progression of lung cancer." (PMID 30621612, 2019).
melanoma (4 papers, 2016 to 2022). A malignant, usually aggressive tumor composed of atypical, neoplastic melanocytes. "Overexpression of TNS3 in HEK 293 cells inhibits cell migration, whereas downregulation in human melanoma WM793 cells increases cell migration." (PMID 30850595, 2019).
glioblastoma (3 papers, 2022 to 2025). The most malignant astrocytic tumor (WHO grade IV). "A recent study implicated TNS3 in microglial gene networks in glioblastoma and AD and reported an inverse correlation between TNS3 and APOE expression levels." (PMID 41404291, 2025). "In glioblastoma, Musashi-1 (MSI1), an RNA-binding protein, inhibited TNS3 translation by binding its mRNA 3’UTR, promoting migration." (PMID 40906372, 2025). "In glioblastoma, MSI1 directly interacts with the TNS3 mRNA 3’UTR to inhibit its translation, thereby activating RhoA and promoting migration." (PMID 40906372, 2025).
colon cancer (2 papers, 2014 to 2023). "Taken together, these results are consistent with the hypothesis that a switch toward CTEN rather than tensin-3 expression is associated with increased colon cancer cell metastasis." (PMID 24884630, 2014). "TNS1, TNS3 and TNS4 knockdown reduces the proliferation of several cancer cell lines, such as colon cancer and acute myeloid leukemia cell lines." (PMID 37510408, 2023).
esophageal squamous cell carcinoma (2 papers, 2021 to 2025). Esophageal squamous cell carcinoma (ESCC) is a type of esophageal carcinoma (EC) that can affect any part of the esophagus, but is usually located in the upper or middle third. "Moreover, silencing TNS3 with the histone deacetylase inhibitor LMK-235 inhibited esophageal squamous cell carcinoma (ESCC) cell proliferation in vitro and in vivo." (PMID 40906372, 2025).
gastric cancer (2 papers, 2021 to 2025). A primary or metastatic malignant neoplasm involving the stomach. "TNS1, TNS2 and TNS3 proteins expression was evaluated in 90 patients with gastric cancer by immunohistochemistry method." (PMID 33926026, 2021). "The expression of TNS1, TNS2 and TNS3 was examined immunohistochemically in 90 gastric cancer samples and 20 normal gastric tissues." (PMID 33926026, 2021). "In contrast, positive expression of TNS2 and TNS3 was observed more frequently in moderately differentiated gastric cancer than in poorly or undifferentiated tumors." (PMID 33926026, 2021). "In gastric cancer, TNS3 exhibits differential effects on tumorigenesis versus metastasis." (PMID 40906372, 2025). "Analysis of TNS1–3 expression in 90 gastric cancer patients revealed that the TNS3 protein was more frequent in moderately differentiated tumors compared to poorly/non-differentiated types, suggesting a potential role in promoting tumorigenesis rather than metastasis." (PMID 40906372, 2025).
kidney cancer (2 papers, 2021 to 2023). Primary or metastatic malignant neoplasm involving the kidney. "It was also shown that patients with kidney cancer and TNS3 detected in their cell membrane prognosed better survival than those lacking TNS3 or with TNS3 present only in the cytoplasm." (PMID 33926026, 2021).
thyroid carcinoma (2 papers, 2021 to 2025). "TNS3 was observed with high mRNA levels in normal thyroid tissues but low levels in most thyroid carcinomas and non-functioning thyroid follicular adenomas, suggesting a tumor-suppressive role in thyroid cancer." (PMID 40906372, 2025).
allergic asthma (1 paper, 2011). A asthma with a basis in a pathological type I hypersensitivity reaction. "RYR2, CHRM2 and TNS3 polymorphysms were confirmed as associated with allergic asthma onset risk in an independent pediatric population." (PMID 21359210, 2011).
Alzheimer disease (1 paper, 2025). A progressive, neurodegenerative disease characterized by loss of function and death of nerve cells in several areas of the brain leading to loss of cognitive function such as memory and language. "Further, TNS3 interacts with AD-related druggable genes EGF and HGF, which in turn interact with EGFR (eFigure-11), a gene that was recently implicated in Alzheimer’s disease through GWAS15 and itself shows strong potential as a dual drug target for cancer and AD68." (PMID 41404291, 2025).
anxiety disorder (1 paper, 2024). A category of psychiatric disorders which are characterized by anxious feelings or fear often accompanied by physical symptoms associated with anxiety. "For anxiety disorders, 18 SNPs are linked to genes including CAMKMT, ARPP19, SOCS5, TNS3, VWDE, TSHZ2, and others." (PMID 39165506, 2024). "Genes related to metal binding or metal ion binding (e.g., ATP9B, LMAN2L, TNS3, and TSHZ2) may play a role in the development of anxiety disorders." (PMID 39165506, 2024).
breast invasive carcinoma (1 paper, 2021). "Investigation of TCGA datasets also indicated that MLL3 and TNS3 are positively correlated in multiple types of cancers, including CESC, UCEC, breast invasive carcinoma (BRCA), PRAD, COAD, liver hepatocellular carcinoma (LIHC), stomach adenocarcinoma (STAD) and KIRC." (PMID 33824309, 2021).
colorectal cancer (1 paper, 2025). A primary or metastatic malignant neoplasm that affects the colon or rectum. "Furthermore, in colorectal cancer cells, the EGFR/Kras pathway specifically upregulates TNS4, though without affecting TNS3, and in HeLa cells, the EGFR-activated RAF/MEK/ERK pathway facilitates p300 binding to the TNS4 promoter, enhancing its expression." (PMID 40906372, 2025).
ductal pancreatic adenocarcinoma (1 paper, 2026). "TNS2 and TNS3 are not involved in the development of ductal pancreatic adenocarcinoma." (PMID 41923376, 2026).
hypogonadotropic hypogonadism (1 paper, 2013). Abnormal ovarian or testicular function due to insufficient hormonal stimulation from the hypothalamic-pituitary axis. "Interestingly, a separate study has identified a different balanced translocation involving the TNS3 gene, in this case also affecting the FGFR1 gene, with the patient displaying hypogonadotropic hypogonadism and cleft lip and palate." (PMID 23809228, 2013).
lipoma (1 paper, 2019). A benign, usually painless, well-circumscribed lipomatous tumor composed of adipose tissue. "Specifically, LPP (lipoma preferred partner/LIM domain containing preferred translocation partner in lipoma), TNS3 (Tensin 3) and NR5A2 (nuclear receptor subfamily 5 group A member 2) encode proteins important in cell adhesion and migration." (PMID 30621612, 2019).
myeloproliferative disorder (1 paper, 2020). A clonal hematopoietic stem cell disorder, characterized by proliferation in the bone marrow of one or more of the myeloid (i.e., granulocytic, erythroid, megakaryocytic, and mast cell) lineages. "For instance two CpG sites were within genes, TNS3 and FGFR1OP, that can interact with and potentially influence the function of the fibroblast growth factor receptor (FGFR), and which has previously been observed in cases of developmental disorder and myeloproliferative disorder, respectively." (PMID 33076993, 2020).
polydactyly (1 paper, 2024). A disease characterized by the presence of polydactyly, including syndromic and non-syndromic forms. "A total of 151 SNP loci significantly correlated with the polydactyly trait were identified through GWAS, and five genes, R-spondin 4 (RSPO4), tensin-3 (TNS3), chloride channel 7 (CLCN7), SLC52A3, and ANGPT4, were annotated to be significantly correlated with polydactyly." (PMID 38612286, 2024).
renal cell carcinoma (1 paper, 2025). "Additionally, elevated TNS3 mRNA levels correlated with decreased migration and invasion in malignant thyroid cell lines, TNS3 promoter hypermethylation was linked to renal cell carcinoma (RCC) metastasis, and mixed-lineage leukemia 3 (MLL3)-activated TNS3 suppressed U2OS cell migration." (PMID 40906372, 2025).
cancer (23 papers, 2011 to 2025). A tumor composed of atypical neoplastic, often pleomorphic cells that invade other tissues. "Overall, these data indicated that the TNS3 short isoform was associated with poor prognosis in a wide range of cancer types, although confirmation of this association will require additional investigation in a larger cohort." (PMID 34811492, 2021). "Here, we have shown that PKA is present and active within FAs and have identified several new putative FA substrates for PKA, including Tns3, a regulator of adhesion, migration, and cancer cell invasion and of signaling events associated with those cellular processes." (PMID 38552737, 2024). "Consistently, stable TNS3 expression in HEK293 cells suppressed migration and matrix invasion, while TNS3 knockdown increased migration in human cancer cells." (PMID 40906372, 2025). "This negative affect factor was found to be negatively correlating with cg23768860, which is localized in proximity of the TNS3 gene (Tensin 3), which is involved in signal transduction and cancer." (PMID 37626570, 2023). "Exogenous expression of SUV4-20H2 in breast cancer cells inhibited the metastatic potential of cancer cells by suppressing the expression of genes involved in cancer migration, such as tensin-3 and focal adhesion." (PMID 38036730, 2023). "These indicate that the regulation of MLL3 on TNS3 expression is quite common in cancer cells, which is consistent with the previous study (Sup." (PMID 33824309, 2021). "Considering MLL3’s role in transcription and cancer, we deduced that TNS3 probably is the direct target gene for MLL3 to regulate cell migration." (PMID 33824309, 2021). "Our study identified the enhancer for TNS3 gene in MLL3 deficient cells, which will be important to understand how MLL3 suppresses cancer and the related future studies." (PMID 33824309, 2021). "To further investigate the relationship between MLL3 and TNS3 in cancers, we examined the protein expression in the tumors derived from MLL3 deficient HeLa cells." (PMID 33824309, 2021). "Since MLL3 acts as a tumor-suppressive gene in multiple cancer types, we examined its function on TNS3 in several cancer cell lines, including U2OS, HeLa, 769-P, and MDA-MB-231." (PMID 33824309, 2021). "STAB1, TM4SF1, and TNS3 are involved in cell adhesion and motility, which are relevant to cancer metastasis and invasion, however, their roles in interaction between leukemic stem cells and bone marrow niche deserve further investigation." (PMID 26517675, 2015). "The cancer related category apoptosis was over-represented with both up- and down-regulated genes, represented by two up-regulated genes (TNS3, EMP1) and five genes down-regulated (DNASE1L2, CXCR4, Gal-7, FKBP5, SGK1)." (PMID 25867603, 2015). "This highlights TNS3’s role in modulating the tumor microenvironment beyond cancer cell-autonomous effects, where variable compositions of stromal cells may further impact tensin functionality." (PMID 40906372, 2025). "Clinical and mechanistic profiles of TNS3 in different cancers." (PMID 40906372, 2025). "Functions of TNS3 in cancer exhibit cancer type and cell context specificities." (PMID 40906372, 2025). "TNS3 promotes cell migration and invasion through focal adhesion dynamics, which is critical in cancer metastasis." (PMID 41247789, 2025). "Importantly, Tns3 expression is variably up- or downregulated in various cancers and has often been demonstrated to suppress or govern cell motility and invasion." (PMID 38552737, 2024). "Recently, it was reported that TNS3 contributes to oncogenesis in human cancer cell lines." (PMID 31905841, 2019). "The current study identified tensin 3 (TNS3) as a target gene for MLL3, which is critical for regulating cancer cell migration." (PMID 33824309, 2021). "The oncogenic role of TNS3 in cancers could be mainly attributed to Src family kinases (SFKs, mainly Src), which mediate phosphorylation of SH2 domains of TNS3." (PMID 34047714, 2021).